INS (insulin)
Diseases named in the same sentence as INS in open-access papers (continued):
Sharing a sentence is not in itself a finding about the gene and the disease.
type 2 diabetes (continued). "Fasting PP was weakly positively correlated with HOMA2-IR in individuals with type 2 diabetes not using exogenous insulin (r = 0.1, p < 0.05), but not significantly correlated with HOMA-%B or HOMA-%S." (PMID 38850100, 2024). "The mechanisms mediating the complex insulin secretory dynamics have both fundamental and clinical significance, as the first-phase is absent (or attenuated) in IVGTT’s performed on patients with Type 2 diabetes mellitus." (PMID 38989001, 2024). "These autoimmune-positive individuals are more likely to become insulin-dependent earlier than individuals with autoantibody-negative type 2 diabetes." (PMID 39329041, 2024). "Intriguingly, the treatment of diabetic mice with the HIF-1α inhibitor PX-478 improves insulin secretion and glucose tolerance, suggesting that the inhibition of HIF-1α might be a potential treatment for type 2 diabetes." (PMID 38673770, 2024). "Since another benefit of carnosine has been shown in its ability to increase serum insulin concentrations and thus to reduce serum glucose levels, CN1 may influence hyperglycemia in type 1 diabetes to a lesser extent than in type 2 diabetes." (PMID 38932803, 2024). "Twenty-five of the newly diagnosed patients were followed for at least 12 months, and 11 (44%) of them were not using insulin and exhibited metabolic features of type 2 diabetes." (PMID 39033190, 2024). "We also report a potent reduction in circulating NEFA concentrations after KME ingestion compared with CON ingestion in individuals with type 2 diabetes, in the absence of a difference in circulating insulin levels between conditions." (PMID 38483543, 2024). "Type 2 diabetes mellitus (T2DM) is a multifactorial disease involving lifestyle and nutritional status, characterized by the impairment of insulin secretion, insulin resistance (IR), or the combination of both, bringing about persistent inflammation and hyperglycemia." (PMID 39525505, 2024). "One study found that while light therapy did not affect insulin sensitivity in type 2 diabetic patients, it did have a positive effect on depressive symptoms in type 2 diabetic patients with high insulin resistance." (PMID 38375195, 2024). "So, the low ω-6 to ω-3 PUFA ratio diet highlights a specific pathway related to a low ω-6 to ω-3 PUFA ratio, which, by itself, improves insulin clearance in NAFLD patients, making it potentially useful in type 2 diabetes, obese people, and, possibly, type 1 diabetes." (PMID 39519472, 2024). "This study demonstrated that once-weekly insulin icodec achieved superior glycemic control in patients with type 2 diabetes compared to once-weekly insulin FC, without significant differences of hypoglycemia." (PMID 38172995, 2024). "This is consistent with the outcomes of previous studies in people with type 2 diabetes, in which metformin, even after sustained exposure, did not affect insulin sensitivity, as assessed using hyperinsulinaemic–euglycaemic clamp techniques." (PMID 38561463, 2024). "In the SURPASS-5 phase III study, subcutaneous tirzepatide was added to titrated insulin glargine, and produced statistically significant improvements in glycemic control among patients with type II diabetes mellitus, as opposed to a placebo." (PMID 39457606, 2024). "In the more common type 2 diabetes, lack of tissue sensitivity to insulin and impaired regulation of glucose production lead to impaired β-cell functionality and, eventually, β-cell dysfunction." (PMID 38880916, 2024). "The impact of SGLT2 inhibitors on patients with poor insulin reserves, including those with type 1 diabetes or living with LADA, may vary from that on those with type 2 diabetes." (PMID 39598463, 2024). "In contrast, subjects with type 2 diabetes with or without insulin treatment showed only a transient increase in glucose variability and no changes in glycemic control measures during RF." (PMID 39203800, 2024).
type 2 diabetes (continued). "Patients with type II diabetes usually do not completely lose the capability for insulin production; in contrast, some patients even have high-level insulin production in the body." (PMID 39420727, 2024). "Studies on RF conducted in individuals with well-controlled type 2 diabetes with or without insulin treatment showed similar results." (PMID 39203800, 2024). "Despite an albeit modest increase in serum magnesium concentration, oral magnesium supplementation does not improve insulin sensitivity in people with insulin-treated type 2 diabetes and low magnesium levels." (PMID 37922013, 2024). "Type 2 diabetes (T2DM) is a chronic and highly heterogeneous progressive disease characterized by both inherited and acquired insulin resistance, along with disturbances in qualitative and quantitative insulin secretion." (PMID 39280993, 2024). "Meanwhile, type 2 diabetes occurs when there is insulin resistance or when the pancreas does not produce enough insulin." (PMID 39130077, 2024). "The prevalence of type 2 diabetes mellitus (T2DM) is higher in HD patients, suggesting that impaired insulin sensitivity may contribute to neurodegeneration in HD." (PMID 39574978, 2024). "Type 2 diabetes is the most common type, usually in adults, which occurs when the body becomes resistant to insulin or does not make enough insulin." (PMID 39456763, 2024). "In a randomized, double-blind, placebo-controlled study, administering 100 mg of CBD twice daily for 13 weeks positively impacted insulin resistance and glucose-dependent insulinotropic peptide in non-insulin-treated type 2 diabetes patients." (PMID 38397045, 2024). "Until now, previous research focused on patients without type 2 diabetes, or patients with type 2 diabetes with relatively well-preserved beta-cell function (insulin-independent) that are in the early stages of the disease process." (PMID 38589596, 2024). "Type 2 diabetes (T2D) occurs when insulin secretion from pancreatic β-cells fails to meet peripheral demand, which is increased with insulin resistance often coincident with obesity." (PMID 38184650, 2024). "Also, GSH/GSSG is significant lower in type 2 diabetic patients and insulin increased GSH/GSSG, suggesting insulin can reduce oxidative stress by controlling GSH redox status." (PMID 39411175, 2024). "In the current study, we sought to provide insight into postprandial insulin kinetics following the ingestion of a standardised mixed-macronutrient breakfast meal in people with and without type 2 diabetes." (PMID 39138690, 2024). "If pancreatic β-cells are damaged, insulin is no longer produced by them, resulting in the development of a prediabetic state and subsequent type II diabetes." (PMID 39796443, 2024). "In type 2 diabetes, the first phase of insulin secretion is impaired or even absent and the second phase is decreased." (PMID 39013634, 2024). "Type 2 diabetes arises when the body’s insulin-sensitive tissues do not effectively respond to insulin, and there is insufficient production of insulin to compensate for this resistance." (PMID 38727474, 2024). "Knowing that both insulin and amyloid-beta (Aβ) are broken down by the insulin-degrading enzyme (IDE), long-standing insulin resistance particularly centrally goes beyond the development of type 2 diabetes to impair neural and cognitive functions." (PMID 39204160, 2024). "Another study demonstrated that people with type 2 diabetes preferred connected over non-connected insulin pens because of the capability for automated recording of insulin dose and glucose levels." (PMID 38951212, 2024). "In another study conducted on 253 patients with type 2 diabetes, the patients were stratified into two groups: patients receiving sitagliptin (a DPP-4 inhibitor) + metformin and/or insulin treatment and patients receiving only metformin and/or insulin treatment." (PMID 38510866, 2024).
type 2 diabetes (continued). "in this review), whereas Type 2 diabetes (T2D) occurs when insulin production fails to meet the demand." (PMID 39125743, 2024). "Maturity-onset diabetes (MODY) is a group of monogenic diseases that result in primary defects in insulin secretion and dominantly inherited forms of non-autoimmune diabetes." (PMID 39902162, 2024). "Patients usually present with symptoms suggestive of type 2 diabetes, and test positive for islet cell antibodies, but do not require insulin therapy at diagnosis and for up to six months thereafter." (PMID 39329041, 2024). "We report an 18-year-old female who presented with symptoms of type 2 diabetes with non-ketotic hyperglycemia, had positive testing for multiple islet cell autoantibodies, but did not require insulin therapy at diagnosis." (PMID 39329041, 2024). "We have previously examined the regulation of regional fatty acid metabolism by insulin alone in nonobese volunteers and in adults with obesity and type 2 diabetes versus obesity alone." (PMID 38602778, 2024). "Our findings suggest that the counterregulatory deficiencies and reduced symptom responses that are common to type 1 diabetes are not present in people with long-standing insulin-treated type 2 diabetes and preserved beta-cell function." (PMID 38376580, 2024). "Second, the consistent association of insulin therapy with fractures, even after adjusting for confounders, suggests that insulin therapy itself (and not just complicated type 2 diabetes) is significant." (PMID 38761257, 2024). "ENSA (Endosulfine Alpha) is also a protein-coding gene that plays a very important role in modulating insulin secretion through the interaction with KATP (ATP-sensitive potassium channel) channel, and this gene has been proposed as a candidate gene for type 2 diabetes." (PMID 38956704, 2024). "Type 2 diabetes mellitus (T2DM), a metabolic condition characterized by chronic hyperglycemia and impaired protein, lipid, and carbohydrate metabolism, can result from either inadequate insulin production or a decreased sensitivity to its metabolic effects." (PMID 39138505, 2024). "It has been demonstrated to ameliorate the impaired glucose homeostasis and insulin sensitivity in type 2 diabetes patients, showing a negative correlation with HDL-C." (PMID 39734674, 2024). "T1D, unlike type 2 diabetes, where there is reduced insulin production or decreased insulin efficiency, is an autoimmune disease characterized by the destruction of the beta cells." (PMID 39590325, 2024). "In Type 2 diabetes, the body either does not produce enough insulin or does not use insulin effectively." (PMID 38371502, 2024). "In conclusion, oral magnesium supplementation does not improve insulin sensitivity in people with insulin-treated type 2 diabetes and a low magnesium level, neither does it affect glucose control, lipid profile, BP and hypomagnesaemia-related symptoms." (PMID 37922013, 2024). "However, in type 2 diabetes (T2D) individuals, hyperglycemia impairs memory CD8+ T cells by insulin-derived GLUT1 upregulation and enhanced glucose uptake." (PMID 39737193, 2024). "Obesity and type 2 diabetes mellitus (T2D) are common metabolic diseases, and a growing body of research suggests that M-EVs play an important role in these metabolic diseases by mediating inflammation and regulating insulin sensitivity, lipid metabolism, glucose uptake, and mitochondrial activity." (PMID 39896803, 2024). "T2DM, type 2 diabetes; T, tertile; WC, waist circumference; BMI, body mass index; BF, body fat; FPG, fasting plasma glucose; HbA1c, glycated hemoglobin; SI, serum insulin; TC, total cholesterol, TG, triglycerides; HDL, high-density lipoprotein; LDL, low-density lipoprotein; Vit." (PMID 38800767, 2024). "As such, glycemic traits likely reflect symptoms of type 2 diabetes while insulin also has a role in the pathophysiology of type 2 diabetes independent of hyperglycemia." (PMID 38459184, 2024).
type 2 diabetes (continued). "It is distinct from type 1 diabetes, in which insulin therapy is required from diagnosis, and from type 2 diabetes, in which insulin therapy is not required at all, or at least not until several years after diagnosis." (PMID 39329041, 2024). "Athletes had higher serum HDL-cholesterol concentrations but lower serum triglycerides, fasting glucose, insulin and plasma non-esterified (free) fatty acids and were highly insulin sensitive whereas patients with type 2 diabetes were insulin resistant." (PMID 38750012, 2024). "In previous studies, insulin was used in all patients, but in this study, the effect on nocturia in patients with type 2 diabetes, including those not on insulin, was examined." (PMID 38826603, 2024). "The main finding of this study is that oral magnesium supplementation, despite significantly increasing the serum magnesium concentration, did not improve insulin sensitivity in people with insulin-treated type 2 diabetes and low magnesium levels." (PMID 37922013, 2024). "The demonstration that the administration of antisense oligonucleotides targeting NNMT to animals led to reduced weight gain and enhanced insulin sensitivity has prompted the development of NNMT inhibitors (NNMTis) for the treatment of obesity and type 2 diabetes." (PMID 38921477, 2024). "The temporal suppression of insulin clearance after glucose ingestion is a key determinant of glucose tolerance for people without type 2 diabetes." (PMID 39138690, 2024). "Patients affected with type 1 diabetes and a non-negligible number of patients with type 2 diabetes are insulin dependent." (PMID 37836872, 2023). "Last, AT-001 treatment also did not affect cardiac insulin signaling, as phosphorylation of Akt at serine 473 was also similar to that observed in vehicle-treated mice with type 2 diabetes." (PMID 36978133, 2023). "Type 2 diabetes eventually develops when pancreatic beta cells do not secrete enough insulin to meet the demands of insulin resistance." (PMID 36839280, 2023). "For example, in type 1 diabetes, the metabolic control network is completely degraded due to lack of endogenous insulin secretion and a need for external insulin replacement, whereas in type 2 diabetes, the metabolic network structure is largely preserved." (PMID 36983362, 2023). "Physical activity, also an important factor in preventing type 2 diabetes independent of body weight status, helps to improve insulin sensitivity, reduce visceral fat, enhance β-cell function and improve gut microbiota." (PMID 37964315, 2023). "Most of our type 2 diabetes patients, treated with low-premixed insulin, did not meet the recommended TBR target for older/high-risk patients while meeting the TIR and TAR targets." (PMID 36882852, 2023). "During obesity progress, proinflammatory macrophages predominate in adipose tissue inflammation, which reduces insulin sensitivity until the development of type 2 diabetes, progression of atherosclerosis, and diagnosis of non-alcoholic fatty liver disease." (PMID 37179836, 2023). "Noninsulin-dependent diabetes mellitus (NIDDM), or type 2 diabetes, is a complex metabolic disorder resulting from either insulin insufficiency or insulin dysfunction, leading to hyperglycemia." (PMID 36837888, 2023). "Once-weekly tirzepatide versus once-daily insulin degludec as add-on to metformin with or without SGLT2 inhibitors in patients with type 2 diabetes (SURPASS-3): a randomised, open-label, parallel-group, phase 3 trial." (PMID 37908927, 2023). "The most common is type 2 diabetes, usually in adults, which occurs when the body becomes resistant to insulin or does not make enough insulin." (PMID 37509542, 2023). "In type 1 diabetes, the pancreas does not produce enough insulin, while in type 2 diabetes, the body is unable to effectively utilize the insulin it produces." (PMID 37512570, 2023).
type 2 diabetes (continued). "Type 1 diabetes (T1D) is an autoimmune disorder resulting from the destruction of the insulin-making cells in the pancreas, while type 2 diabetes (T2D) is due to insulin resistance, which is the case when cells do not respond properly to insulin." (PMID 36902160, 2023). "Type 1 diabetes occurs when the body’s immune system attacks and destroys insulin-producing cells in the pancreas, whereas Type 2 diabetes occurs when the body becomes insulin-resistant or fails to produce enough insulin to regulate blood sugar levels." (PMID 37238305, 2023). "Moreover, the analysis of patients with type 2 diabetes could help confirm whether the increased plasma IL-21 levels in adults with T1D are truly associated with autoimmunity and are not secondary to hyperglycemia and/or exogenous insulin use." (PMID 37415982, 2023). "In some patients with type 2 diabetes with milder degrees of hyperglycemia, a Dipeptidyl peptidase inhibitor can be used with correction insulin, Provided there are no contraindications to using any of them." (PMID 37363479, 2023). "Obesity and type-2 diabetes mellitus are accompanied by the upregulation of inflammatory markers that substantially contribute to an overproduction of ROS/RNS, favoring insulin resistance in peripheral tissues and impaired insulin secretion from the pancreas." (PMID 36843614, 2023). "In type 2 diabetes, the body continuously manufactures insulin, but it does not work correctly due to insulin resistance." (PMID 36908276, 2023). "On the other hand, in type 2 diabetes, the body either develops resistance to insulin or not enough insulin is produced to lower the blood sugars; this is more often due to old age and insulin resistance." (PMID 37255905, 2023). "In adults, developing type 2 diabetes at low body weight is not uncommon, and both ketoacidosis and profound presentation hyperglycaemia occur in non-autoimmune, apparent type 2 diabetes, without requirement for long-term insulin treatment." (PMID 37728732, 2023). "Type 1 diabetes, once so-called juvenile diabetes, occurs when the pancreas does not produce insulin, whereas type 2 diabetes occurs when the body becomes resistant to insulin, and it most often develops in adults." (PMID 36839770, 2023). "In a selected population of individuals with type 2 diabetes on insulin therapy, this study confirmed that the addition of a GLP-1 RA (liraglutide, semaglutide, or dulaglutide) effectively reduced HbA1C, body weight, and insulin requirements." (PMID 37589043, 2023). "The use of Flash CGM in older people with type 2 diabetes receiving insulin treatment is possible regardless of social conditions or schooling, improving the glycemic profile and safety in conditions of high risk of hypoglycemia." (PMID 37993898, 2023). "Biotin levels were found to be lower in individuals with type 2 diabetes and administration of biotin was shown to lower blood glucose level in these individuals without altering the insulin levels." (PMID 36873578, 2023). "Despite the increasing use of insulin to treat T2DM, hypoglycemia and IAH are not thought to pose substantial issues in the treatment of insulin-treated type 2 diabetes (T2DM)." (PMID 36974247, 2023). "The link between higher genetically derived adulthood BMI and higher insulin secretion in people without type 2 diabetes is probably a response to lower insulin sensitivity." (PMID 37280435, 2023). "Of note, unlike healthy subjects and people with type 2 diabetes, amino acids, GIP, and GLP-1 are not insulinotropic in people living with T1D because of the loss of endogenous insulin secretion." (PMID 36771250, 2023). "Authors have concluded that chromium's potential to enhance insulin action, rather than insulin secretion, underscores its role in glycemic control for type 2 diabetes patients." (PMID 38024820, 2023). "The Goto-Kakizaki (GK) rats are a non-obese insulin resistant model of type 2 diabetes produced by selective inbreeding for a hyperglycemic phenotype." (PMID 37519334, 2023).